RNU6-81P (RNA, U6 small nuclear 81, pseudogene)
Synonyms: RNU6-81
Gene: Small nuclear RNA gene on chromosome 13 (63,783,801 to 63,783,904, forward strand). Ensembl gene ENSG00000202478.
Homologues: Orthologues: chimpanzee U6 (100% identical), macaque U6 (90% identical), pig U6 (76% identical). Paralogues in human: RNU6-68P (98% identical), RNU6-1131P (84% identical), RNU6-1152P (84% identical), RNU6-15P (84% identical), RNU6-166P (84% identical), RNU6-266P (84% identical), RNU6-536P (84% identical), RNU6-589P (84% identical), RNU6-672P (84% identical), RNU6-869P (84% identical), RNU6-886P (84% identical), RNU6-1011P (83% identical), and 1287 more.